INS (insulin)
Diseases named in the same sentence as INS in open-access papers (continued):
Sharing a sentence is not in itself a finding about the gene and the disease.
diabetes (continued). "As a pathway fundamental to the development of diabetes mellitus, insulin signal transduction involves the phosphatidylinositol 3‐kinase–Akt (protein kinase B) pathway with the downstream involvement of GSK3." (PMID 37139700, 2023). "Insufficient pancreatic β-cell mass and reduced insulin expression are key events in the pathogenesis of diabetes mellitus (DM)." (PMID 37903776, 2023). "PPARγ agonists (thiazolidinediones) are used to treat Type 2 diabetes mellitus by improving insulin sensitivity." (PMID 36768666, 2023). "Rarely, co-existence of WS1 and T1DM has been described in patients diagnosed with diabetes and characterized by positive insulin antibodies, together with other typical features of WS1." (PMID 36835101, 2023). "Harnessing the potential of algae-derived natural products for improving insulin secretion and sensitivity holds great promise for the development of novel therapeutic interventions for diabetes." (PMID 37763235, 2023). "Subsequently, TRPC3 activation through targeted small‐molecule enhances insulin secretion and alleviates diabetes hallmarks in animals." (PMID 36642838, 2023). "There is evidence in the literature that the use of sensor-augmented insulin pumps in patients with high-complexity diabetes improves metabolic control." (PMID 37610810, 2023). "Combining CSII with education and training on nutrition, exercise, and insulin adjustment maximizes its effectiveness in diabetes care, significantly improving glycemic control and reducing hypoglycemia in T1DM patients." (PMID 38068755, 2023). "The improvement of insulin pump application and the strengthening of diabetes management education all contributed to improving the disease burden attributable to type 1 diabetes." (PMID 37400673, 2023). "In the realm of diabetes research, the effects of NOXs on insulin secretion present a complex picture." (PMID 38203517, 2023). "Insulin therapy is the current gold standard of glycemic control in patients with uncontrolled diabetes and is indicated to begin if maximally dosed dual oral therapy is unsuccessful." (PMID 37090383, 2023). "Insulin pump therapy is recommended more and more to achieve and maintain optimal glycaemic control in patients with type 1 diabetes mellitus." (PMID 37185052, 2023). "Due to his advanced age and medical history (especially insulin usage for type 2 diabetes mellitus), we determined that he would have a low tolerance for prosthetic graft replacement and performed TEVAR as an emergency procedure." (PMID 36732803, 2023). "Leptin and soluble leptin receptor levels are increased in T1DM children and related to anthropometrics parameters, metabolic control, age of debut of diabetes, and kind of insulin therapy." (PMID 36674935, 2023). "Guidelines and protocols for diabetes self-management using insulin pumps in the perioperative period were established by the Joint British Diabetes Society in 2011." (PMID 37131168, 2023). "Diabetes is a condition marked by consistently high levels of glucose in the blood due to insufficient insulin secretion, impaired insulin function, or both." (PMID 38283440, 2023). "Islet graft maintained the function of sensing and releasing insulin and reversed diabetes in streptozotocin-induced diabetic SCID mice." (PMID 37106373, 2023). "At the age of four days, a diagnosis of neonatal diabetes was made and subcutaneous insulin was adjusted based on his needs." (PMID 37854477, 2023). "While participants took an average of 7.3 (SD 3.8) total medications, 3 participants (30%) took only oral diabetes medications, 1 participant (10%) took only insulin, and 6 (60%) took both for diabetes." (PMID 37794913, 2023). "Type 1 diabetes mellitus (T1DM) occurs when insulin production is severely impaired by the pancreatic beta cells’ autoimmune destruction." (PMID 37629520, 2023).
diabetes (continued). "Steatosis of the islet beta-cell induces apoptosis, reducing its capacity to produce insulin, and the stage is ready for the appearance of severely insulin-resistant Type 2 diabetes mellitus." (PMID 38260129, 2023). "Apelin regulates insulin secretion, glucose uptake, lipid oxidation, apoptosis, oxidative stress, and angiogenesis, playing a critical role in diabetes-related complications like cardiovascular diseases, diabetic nephropathy, and endothelial dysfunction." (PMID 37424869, 2023). "IL-6 also interacts with the hypothalamic-pituitary-adrenal axis, resulting in increased insulin sensitivity that triggers diabetes, as well as increased BMI and blood pressure that lead to hypertension." (PMID 37900560, 2023). "Many other mechanisms not strictly concerning the autoimmunology process, such as its effect on glucose, insulin, and insulin resistance, are, to a significant degree, common for both types of diabetes." (PMID 36771207, 2023). "Plasma ZAG has previously been shown to be negatively associated with insulin levels and HOMA-IR in humans with normal glucose tolerance, impaired glucose tolerance (IGT), and newly diagnosed type 2 diabetes mellitus (T2DM)." (PMID 37830580, 2023). "The patient had a history of diabetes for more than 3 years, irregularly taking oral medications and insulin therapy." (PMID 37506152, 2023). "Among these products, islet cells are especially relevant for diabetes treatment, as they can produce insulin and regulate blood glucose levels." (PMID 37777562, 2023). "Both the treatment and diagnosis of secondary diabetes is difficult, and involves not only glycemic control by insulin use, but also the treatment of exocrine pancreatic insufficiency through fatty acid enzyme substitutions." (PMID 37373398, 2023). "Insulin pump satisfaction was assessed using the Diabetes Treatment Satisfaction Questionnaire (DTSQ)." (PMID 37185052, 2023). "Glucose trend arrows add important information for appropriate mealtime insulin dosing in patients with intensive insulin-treated diabetes." (PMID 36900956, 2023). "When the function of a protein changes, it affects the subunit function complex and leads to aberrant insulin production, contributing to diabetes." (PMID 37372155, 2023). "Patient awareness of proper insulin storage is essential to ensure the effectiveness of diabetes management." (PMID 37858279, 2023). "Type 1 diabetes mellitus (T1D) is characterized by autoimmune destruction of the pancreatic β-islet cells, the cells responsible for the production of insulin." (PMID 37240215, 2023). "Overall, PLWT1D reported good knowledge and practice of self-management activities, facilitated by extensive diabetes education, provision of free insulin and supplies, home visits, and distribution of transport funds." (PMID 37291520, 2023). "Diabetes mellitus (DM) is a common metabolic condition characterized by hyperglycemia, insulin resistance, and significantly decreased insulin production." (PMID 37223012, 2023). "The history of diabetes treatment has been marked by a continuous effort to develop effective therapies ever since the groundbreaking discovery of insulin by Banting and Best in 1921." (PMID 38283440, 2023). "Diabetes mellitus (DM) is a chronic condition that occurs when the pancreas of the human body cannot produce enough insulin, or the body cannot use it." (PMID 36773970, 2023). "The mean duration of diabetes and the total daily dose of insulin of the participants were 12.8 ± 9.3 years and 43.6 ± 24.2 units, respectively." (PMID 37255973, 2023). "At age 15, she presented with ketoacidosis, HbA1c of 108.7 mmol/mol (12.1%), and positive anti-insulin antibodies." (PMID 37864241, 2023). "Insulin studies tend to recruit patients with a longer duration of diabetes or more severe cases with a higher mortality rate." (PMID 37242426, 2023).
diabetes (continued). "Although insulin also exhibited some improvements in the adverse effects of diabetes, the results indicated that hesperidin was even more potent in counteracting the toxic impact of diabetes on the testes compared to insulin treatment." (PMID 38234970, 2023). "For those who had received education, topics included diabetes symptoms and risk factors, OAM, blood glucose monitoring and insulin." (PMID 37386440, 2023). "In diabetics, this proportion significantly increased in all gut segments, which was prevented by insulin treatment." (PMID 36982878, 2023). "It is now well known that all forms of diabetes commonly share a dysfunction of the pancreatic beta cells that negatively impacts insulin secretion." (PMID 37371672, 2023). "Type 1 diabetes mellitus (T1D) is a multifactorial autoimmune disease characterized by the selective destruction of pancreatic insulin-producing beta cells due to the aberrant activation of different immune effector cells (reviewed (rev [...]." (PMID 37298175, 2023). "Diabetes mellitus is a metabolic disorder characterized by hyperglycemia due to impaired insulin secretion or action." (PMID 37868469, 2023). "Notwithstanding these limitations, this study offers valuable insight to addressing behavior needs for self-management by adults with diabetes requiring insulin therapy." (PMID 36826987, 2023). "Diabetes is caused by either the lack of insulin production by the pancreas, a disease known as type 1 diabetes mellitus (T1DM), or the inability of the cells to react suitably to the insulin produced, a situation known as type 2 diabetes mellitus (T2DM)." (PMID 37317131, 2023). "Diabetes mellitus is characterized by hyperglycemia following defects in insulin secretion or insulin action." (PMID 37049638, 2023). "The present study used a novel long-term (24 weeks) rat model of STZ-induced diabetes with insulin administration, which successfully resembles chronic T1DM characterized by weight loss, polyuria, hyperglycaemia, hyperglycosuria, and higher HbA1c." (PMID 36982322, 2023). "Transdermal drug delivery has also shown promising results in insulin delivery for diabetes patients, offering a convenient and effective alternative to traditional insulin injections." (PMID 37397493, 2023). "The pathophysiology of GC-induced diabetes involves both insulin resistance and impaired insulin production." (PMID 37842314, 2023). "Physical activity (PA) is normally suggested in the management of type 1 (T1DM) and type 2 (T2DM) diabetes mellitus and can improve glucose uptake by increasing insulin sensitivity, glucose transportation into the cells, and lowering body adiposity." (PMID 37998439, 2023). "Both this study and others have suggested that chromium improves insulin sensitivity, leading to decreased blood sugar levels in diabetes patients." (PMID 38024820, 2023). "Even small proteins such as insulin suffer from slow pharmacokinetics which poses limitations in effective management of diabetes." (PMID 36642846, 2023). "In humans with this type of diabetes, blood glucose levels are initially normal or only moderately elevated due to the compensatory hypersecretion of insulin." (PMID 38203600, 2023). "Insulin treatment increases leptin levels (5.18 ± 5.48 ng/ml) in children with newly diagnosed diabetes, which is consistent with our results." (PMID 37670877, 2023). "Diabetes secondary to somatostatinoma is well controlled with oral antidiabetics and diet or, in some cases, with low doses of insulin." (PMID 37628857, 2023). "For example, specific HL scales exist for diabetes by extending the HL scales to be more specific toward diabetes management skills, such as capacity to understand insulin management." (PMID 36652467, 2023). "After induction of diabetes with STZ, diabetic mice were divided into two groups: one group received blank pellets as uncontrolled diabetes, while the other group was treated with insulin pellets." (PMID 37311905, 2023).
diabetes (continued). "Hepatic gluconeogenesis is found to increase in NAFLD and diabetes, which is prevented by acute exercise together with an increased hepatic glycogen content or by chronic exercise through improvement of insulin sensitivity, and agrees with our data." (PMID 36674144, 2023). "Participants on insulin treatment modality had four times higher odds of knowledge on diabetes (B = 4.17, p = 0.023) while those on combined therapy (both oral hypoglycaemic agent and insulin) had 7.26 times higher odds of knowledge (B = 7.26, p < 0.001)." (PMID 36464636, 2023). "Type 1 diabetes mellitus is a metabolic disease that is characterized by the destruction of pancreatic beta cells leading to inadequate insulin production." (PMID 37584373, 2023). "High androgen levels cause hyperinsulinemia, which leads cells to become insulin resistant and makes PCOS patients more likely to develop diabetes mellitus." (PMID 36751233, 2023). "At the age of 7, because fasting blood glucose was 28.0 mmol/L, the patient was diagnosed with “type 1 diabetes mellitus” and treated with insulin injection." (PMID 37974252, 2023). "Several studies have shown that being overweight, having high insulin levels and a history of diabetes are poor prognostic indicators for patients with multiple myeloma." (PMID 36830619, 2023). "These transplanted islets produced insulin and effectively lowered elevated glucose levels, indicating their potential for treating diabetes." (PMID 38017433, 2023). "As compared to T2DM patients without DN, T2DM patients with DN were older, had a longer duration of diagnosed diabetes, and the higher proportion of insulin and lipid-lowering drugs usage." (PMID 38288472, 2023). "A cohort of 23 000 UK patients with insulin‐treated diabetes diagnosed 1972 to 1993 at ages <30, therefore almost all with type 1 diabetes, were followed for average 30 years, considerably longer than in any published study." (PMID 37190903, 2023). "First, insulin use in patients with diabetes and thiazide use in patients with hypertension are considered independent risk factors for hypokalemia." (PMID 37710182, 2023). "When pancreatic β-cells become dysfunctional and insulin secretion is insufficient, blood glucose levels rise dramatically, leading to the gradual development of diabetes." (PMID 38025699, 2023). "Diabetes mellitus is characterized by chronic hyperglycemia with disturbances in carbohydrate, fat and protein metabolism, resulting from defects in insulin secretion and/or action." (PMID 37816730, 2023). "Diabetes is a medical condition characterized by elevated blood glucose levels resulting from insufficient insulin production or impaired insulin function." (PMID 37724233, 2023). "Type 1 DM (T1DM), previously known as insulin-dependent diabetes mellitus, is characterized by the autoimmune destruction of pancreatic beta cells, which are responsible for the production of insulin." (PMID 37298274, 2023). "Quercetin exhibits neuroprotective effects in Alzheimer's disease (AD) by targeting P13 kinase, AKT/PKB tyrosine kinase, and protein kinase C. It enhances insulin sensitivity and glucose metabolism, suggesting its potential in diabetes treatment." (PMID 37872245, 2023). "The treatment of diabetes involves many aspects, including nutritional therapy, insulin therapy, antidiabetic drug therapy, health education, etc.." (PMID 38002152, 2023). "Such efforts include improved access and equity to continuous glucose monitoring, automated insulin delivery and diabetes psychosocial support, education and nutrition." (PMID 37870651, 2023). "Alloxan induces diabetes by destroying the β‐cells of the islets of Langerhans in the pancreas prompt a decreased degree of endogenous insulin accordingly influencing glucose uptake by tissue." (PMID 37038362, 2023). "For example, syringe pumps are used for continuous subcutaneous insulin infusion (CSII) in diabetes outpatient care via insulin pumps." (PMID 37779821, 2023).
diabetes (continued). "For established individuals with diabetes, constant monitoring of their blood glucose concentration is crucial so that appropriate insulin dosage can be administered in a timely manner to avoid acute and chronic complications and delay disease progression." (PMID 38875549, 2023). "This type of diabetes is typically diagnosed during childhood or adolescence and requires lifelong insulin therapy." (PMID 37600709, 2023). "From a pharmacologic standpoint, the choice of anti-diabetes medications should prioritize those that increase insulin sensitivity and promote weight reduction and deprioritize anti-diabetes medications that increase insulin exposure and promote weight gain." (PMID 37990681, 2023). "The MFP model was selected to be the final model, including gender, the use of insulin, duration of diabetes, urinary albumin-to-creatinine ratio, and serum phosphorus." (PMID 37008912, 2023). "Type 2 diabetes mellitus accounts for over 90% of all diabetes worldwide and is characterized by chronic hyperglycemia and insulin resistance resulting from lifestyle and genetic factors." (PMID 36993806, 2023). "Along with insulin, a healthy diet, regular physical activity, and regular blood glucose monitoring are crucial for effective diabetes management." (PMID 38089047, 2023). "The anthocyanins contained in fruit improve insulin sensitivity through complex biochemical mechanisms, thus potentially preventing diabetes." (PMID 37763199, 2023). "In large measure, the research into T1DM treatment is focused on advanced technologies including insulin pumps, continuous glucose monitoring, the artificial pancreas and various applications to support CC and diabetes management." (PMID 36750449, 2023). "Diabetes mellitus (DM) is a severe chronic metabolic disease characterized by persistent elevation of collective blood glucose levels due to defective insulin secretion and resistance." (PMID 37238782, 2023). "With the continuous research on the physiological function of insulin, a number of new targets for the treatment of diabetes have been discovered." (PMID 37965892, 2023). "Aside from taking ART, participants also had to monitor and take medications for their other conditions, including pills for hypertension or insulin injections or metformin and some had to monitor their blood sugars to help manage their diabetes." (PMID 37064034, 2023). "Study purpose: To analyze the behavioral intentions of wearable insulin biosensors among diabetes patients, the factors that drive or hinder their usage, and the implications for diabetes management and healthcare outcomes." (PMID 38239544, 2023). "PCR was detected as negative in all cases, along with an increase in inflammatory markers, and the patients recovered rapidly with subcutaneous insulin therapy that was tapered off to oral medication for diabetes." (PMID 38022276, 2023). "Research has indicated that a family history of diabetes can influence insulin resistance and insulin secretion, as observed in the Chinese population." (PMID 38054122, 2023). "Childhood obesity is linked to various metabolic complications, including dyslipidemia, decreased insulin sensitivity, increased circulating insulin levels, glucose intolerance, type 2 diabetes mellitus, and metabolic syndrome." (PMID 37189885, 2023). "Increased insulin secretion by pancreatic islet beta cells gradually leads to their exhaustion and the development of pre-diabetic states and diabetes." (PMID 37887427, 2023). "There are two types of diabetes mellitus, namely, type 1 (insulin-dependent) and type 2 (non-insulin-dependent), also known as adult-onset diabetes." (PMID 37239204, 2023). "Increased levels of inflammation diminish IRS-1 expression and disrupt insulin signaling, resulting in elderly diabetes." (PMID 38273819, 2023).